BRCA1 (BRCA1 DNA repair associated)
Diseases named in the same sentence as BRCA1 in open-access papers (continued):
Sharing a sentence is not in itself a finding about the gene and the disease.
ovarian carcinoma (continued). "Regarding to histological subtype of ovarian cancer patients, there was statistically significant difference between BRCA1/2 mutation carriers and non‐BRCA mutation carriers in histological subtype (p = 0.011)." (PMID 30972954, 2019). "We report the presence of BRCA1/2 and non-BRCA1/2 variants in a cohort of individuals with a personal or family history of breast and/or ovarian cancer." (PMID 31125277, 2019). "KJ-28d inhibited PARP-1/2 activities and displayed significant antitumor activity in human ovarian cancer BRCA1-deficient (BRCA1 mutation at 5564G>A) SNU-251 cells." (PMID 31795418, 2019). "Families with mutations in these genes usually have several members affected; carriers of mutations in BRCA1 have a 70–80% chance of developing the disease, and their risk of developing ovarian cancer is 40%." (PMID 31341521, 2019). "A correlation was found of Q356R BRCA1 gene polymorphism with ovarian cancer in the examined patients." (PMID 30712190, 2019). "Further, the favorable results of SOLO1 showed that Olaparib provided a substantial clinical benefit among women in newly diagnosed advanced ovarian cancer with a BRCA1/2 mutation." (PMID 31775908, 2019). "Women with germline BRCA1 mutations have an inherited predisposition to breast- and ovarian cancer, with lifetime risks of 60–80% and 40–60%, respectively." (PMID 31213009, 2019). "A total of 54 (23.3%) ovarian cancer patients were found to harbor BRCA1/2 deleterious mutations, and BRCA1/2 mutations were significantly associated with Hereditary Breast and Ovarian Cancer‐related tumors and family history of cancer." (PMID 30972954, 2019). "About 5–10% of ovarian cancer included hereditary ovarian cancer and about 95% of these patients had BRCA1/2 mutations." (PMID 31689961, 2019). "Women who carry a BRCA1 or BRCA2 gene mutation are at highest risk of developing ovarian cancer, with a lifetime risk of up to 44% by 80 years of age." (PMID 31061661, 2019). "The contribution of high-penetrance alleles of BRCA1/2 can only account for a small part of the heritable component of ovarian cancer." (PMID 30813239, 2019). "Our observation of a positive association between BMI and ovarian cancer risk in premenopausal BRCA1/2 mutation carriers is consistent with findings in the general population." (PMID 31213659, 2019). "Even though the final version of the framework was approved by the GENISAP experts, to gain first-hand experience we are currently validating it by assessing the BRCA1/2 genetic test for susceptibility to breast and ovarian cancer." (PMID 31381569, 2019). "The mutation of some genes has also been associated with an increased risk of epithelial ovarian cancer, such as BRCA1 and BRCA2, BRIP1, RAD51C and RAD51D." (PMID 31182132, 2019). "Data from retrospective ovarian cancer tumor sample analysis suggests that BRCA1/2 loss occurs early in the course of the disease but it is not currently known if this is true in PDAC." (PMID 31835379, 2019). "Olaparib, an oral poly(adenosine diphosphate-ribose)polymerase (PARP) inhibitor, has been approved for the treatment strategy of ovarian cancer with any BRCA1/2 mutations." (PMID 31577767, 2019). "The BRCA1 c.4096+3A>G variant is pathogenic and confers an increased risk of both breast and ovarian cancers." (PMID 31683985, 2019). "Ovarian cancer patients with BRCA1/2 mutations will most likely benefit from PARP inhibitors compared to non‐BRCA mutated patients." (PMID 30972954, 2019). "Breast cell lines were chosen for analysis in this study on CTDP1 because a subset of BRCT domain-containing proteins are known hereditary breast and ovarian cancer susceptibility genes, such as BRCA1 and BRCA234." (PMID 31240132, 2019). "It is supposed that more than 90% of hereditary cases of BC (and also ovarian cancer) are a result of a mutation in BRCA1/2." (PMID 31200461, 2019).
ovarian carcinoma (continued). "We previously reported on a poly (ADP-ribose) polymerase (PARP) 1/2 inhibitor N-(3-(hydroxycarbamoyl)phenyl)carboxamide (designated KJ-28d), which increased the death of human ovarian cancer BRCA1-deficient SNU-251 cells." (PMID 31795418, 2019). "In conclusion, we analyzed serum tumor markers and the prevalence of BRCA1/2 germline mutations in Chinese ovarian cancer patients." (PMID 30972954, 2019). "NCT02571725 is a phase I/II study of olaparib at a dose of 300 mg twice a day (bis in die—BID), in combination with tremelimumab at a dose of 10 mg/kg monthly, for the treatment of BRCA1/2 mutated recurrent ovarian cancer." (PMID 31374917, 2019). "We use the atlas to analyze the presence and type of single point mutations in BRCA1 from samples of human breast and ovarian cancer cell lines." (PMID 30783107, 2019). "For BRCA1 mutation carriers under surveillance, BC and ovarian cancer were the main causes of death." (PMID 31302855, 2019). "BRCA1 mutation confer a genetic susceptibility to ovarian cancer by almost 60%, however in further studies will be interesting to evaluate the influence of BRCA2 mutation." (PMID 30630446, 2019). "BRCA1 is known as a tumor suppressor gene for breast and ovarian cancer, and belongs to the family of ataxia-telangiectasia-mutated-mediated DNA double-strand break (DSB) repair genes and plays a critical role in homology-directed repair of DSBs." (PMID 31167348, 2019). "Methods: 255 BRCA1/2-negative Chinese familial breast and/or ovarian cancer (FBOC) patients were recruited for FANCC germline mutations screen." (PMID 30967997, 2019). "Ovarian cancers are known to develop in younger women with germline BRCA1/2 mutations than otherwise." (PMID 31064392, 2019). "The present findings provide insight into the regulatory relationship between BRCA1 and autophagy and enhance our understanding of the molecular mechanisms underlying BRCA1‐associated ovarian cancer cisplatin resistance." (PMID 30636383, 2019). "With the introduction of the first synthetic lethal drug (the PARP inhibitor olaparib in ovarian cancer with BRCA1 mutation), research into synthetic lethality has also become a hotspot." (PMID 31590683, 2019). "This has relevance for some therapeutic agents, such as poly (ADP-ribose) polymerase (PARP) inhibitors for ovarian cancers with BRCA1/2 mutations." (PMID 31004097, 2019). "In a Swedish study, BRCA1/2 mutations were found in 9% of the women who had first- or second-degree relatives with breast or ovarian carcinomas." (PMID 30713775, 2019). "In this context, somatic BRCA1/2 mutations were predicted to restore the protein function in the germline BRCA1/2 mutated ovarian cancer patients in a study." (PMID 31109041, 2019). "Breast and ovarian cancer patients with tumors harboring somatic or germline BRCA1 mutations have demonstrated robust and lasting responses to PARP inhibitor (PARPi) treatments." (PMID 31827092, 2019). "Nevertheless, a phase II trial of talazoparib in recurrent BRCA1/2-mutated ovarian cancer patients, following primary progression on prior PARP inhibitor, has recently been completed (NCT02326844)." (PMID 31109041, 2019). "More recently, the international phase III SOLO2 study evaluated olaparib as maintenance therapy in platinum-sensitive, relapsed ovarian cancer patients with a BRCA1/2 mutation treated with at least two lines of previous chemotherapy." (PMID 31109041, 2019). "The presented study demonstrated a significant association of studied 135G/C and Q356R polymorphisms of RAD51 and BRCA1 genes, respectively, with the occurrence of ovarian cancer." (PMID 30712190, 2019). "Women who carry a BRCA1/2 pathogenic variant have substantially increased lifetime risks for breast and ovarian cancer compared to the general population." (PMID 31083288, 2019).
ovarian carcinoma (continued). "PARP inhibition demonstrated potent therapeutic efficacies in patients who were diagnosed with either metastatic breast or advanced ovarian cancers with germline BRCA1/2 mutations." (PMID 31771620, 2019). "A recent prospective cohort study estimated the cumulative ovarian cancer risk to age 80 years as 44% (95% confidence interval [CI], 36–53%) for BRCA1 and 17% (95% CI, 11–25%) for BRCA2 mutation carriers." (PMID 31064392, 2019). "Olaparib is the first PARPi approved for the treatment of refractory ovarian cancer harboring BRCA1 or BRCA2 mutations." (PMID 31795418, 2019). "Strickland and coworkers demonstrated that a higher neoantigen load in the BRCA1/2-mutated ovarian cancers compared to HR-proficient tumors translates to a significantly higher number of CD3+ TILs compared to HR-proficient tumors." (PMID 31130614, 2019). "BRCA1/2 mutations have a lifetime risk of causing ovarian cancer in 15–65% of carriers at the age of 70 years." (PMID 31689961, 2019). "Despite data confirming the involvement of BRCA1 in the regulation of drug resistance, the mechanism underlying the BRCA1‐mediated resistance of ovarian cancer cells remains uncertain." (PMID 30636383, 2019). "In this study cohort of 253 women, 213 had BRCA1 variants and only 40 had BRCA2 variants, which affects the generalizability as BRCA1 is associated with a higher risk of both breast and ovarian cancer." (PMID 31888263, 2019). "Single nucleotide polymorphisms (SNPs) in DNA glycosylase genes involved in the base excision repair (BER) pathway can modify breast and ovarian cancer risk in BRCA1 and BRCA2 mutation carriers." (PMID 30747491, 2019). "RING finger and BRCT domains are the most conserved regions of BRCA1 and mutations in these domains are in close association with hereditary breast and ovarian cancer development." (PMID 32042831, 2019). "Mutation of either site disrupts BRCA1 promoter activity in ovarian cancer cell lines, demonstrating that both are required for full transcriptional activation of the BRCA1 promoter in these cells." (PMID 31604914, 2019). "Hereditary predisposition is responsible for 14–24% of ovarian cancers, with the majority attributable to inherited mutations in the BRCA1 or BRCA2 genes." (PMID 30646939, 2019). "We found the association between BRCA1/2 germline mutation status and serum tumor marker levels, and identified discriminative models that combined serum tumor markers with BRCA1/2 mutation status for ovarian cancer detection and patient stratification." (PMID 30972954, 2019). "The ovarian cancer TCGA confirmed a frequency of 17% germline pathogenic variants in BRCA1 or BRCA2 in 489 unselected ovarian cancer cases." (PMID 30606148, 2019). "With respect to the current review, evidence linking BRCA1/2 methylation to cancer risk has so far only been collected from patients with breast and ovarian cancer." (PMID 31225507, 2019). "Bilateral salpingectomy can reduce the risk of ovarian carcinoma for women with BRCA1/2 gene mutations or general population." (PMID 30917839, 2019). "This study showed a similar activity and a trend toward improvement with olaparib versus PLD in patients with relapsed ovarian cancer and BRCA1 or BRCA2 mutations." (PMID 30820349, 2019). "Individuals who inherit BRCA1/2 germline mutations showed a high lifetime risk and early onset of ovarian cancer." (PMID 30972954, 2019). "Female carriers of pathogenic variants of the BRCA1 (path_BRCA1) gene have risks for breast and ovarian cancer." (PMID 30678073, 2019). "Although alkylating agents display similar selectivity to cisplatin in targeting BRCA1/2‐deficiencies, they have largely been abandoned for clinical use in breast and ovarian cancers, due to early sub‐optimal results in non‐stratified patient populations." (PMID 31273933, 2019).
ovarian carcinoma (continued). "Recently, Moghadasi and colleagues estimated that the cumulative risk of breast and ovarian cancer by the age of 70 years was 20% and 6%, respectively, in the carriers with BRCA1 mutation c.5096G>A (p.Arg1699Gln)." (PMID 30968603, 2019). "Nowadays CHK2 mutation is studied frequently in hereditary breast and ovarian cancer patients in addition to BRCA1/BRCA2." (PMID 31398194, 2019). "Originally, the potent anti-cancer effect of PARPi was found in BRCA1/2 deficient ovarian cancer patients." (PMID 31521196, 2019). "The discriminative models with serum tumor markers and BRCA1/2 mutation status were also established for ovarian cancer detection and patient stratification." (PMID 30972954, 2019). "Since more than two decades Risk-reducing salpingo-oophorectomy (RRSO) is recommended and widely accepted by BRCA1/2 carriers as a method reducing ovarian cancer risk and improving survival rate." (PMID 30918533, 2019). "Olaparib is now routinely applied as maintenance treatment for patients with platinum-sensitive recurrent, BRCA1/2-mutated ovarian cancer." (PMID 31029168, 2019). "Mutations in BRCA1/2 that impair HR are commonly found in breast and ovarian cancers and increase sensitivity to PARP inhibitors." (PMID 31619012, 2019). "In Part 2A (phase II), 42 patients with recurrent, platinum-sensitive ovarian cancer, and germline BRCA1/2 mutations, who were previously treated with two to four lines of chemotherapy, received maintenance rucaparib 600 mg bid." (PMID 31109041, 2019). "Poly-(ADP-ribose) polymerase inhibitors (PARPi) selectively kill breast and ovarian cancers with defects in homologous recombination (HR) caused by BRCA1/2 mutations." (PMID 30874560, 2019). "Breast and ovarian cancers related to BRCA1 and BRCA2 mutations tend to occur more often in younger ages than their nonhereditary counterparts." (PMID 30975222, 2019). "This is comparable to high risk populations identified through genetic testing; the lifetime risk for ovarian cancer increases 27 and 11 times with BRCA1 and BRCA2 mutations, respectively." (PMID 33693347, 2019). "A recent study found that 3.6% of ovarian cancer patients have germline mutations in BRCA1 while 3.3% have germline mutations in BRCA2." (PMID 30813239, 2019). "Since 34% of our patients had a germline BRCA1/2 mutation, it is surprising that only 8/44 of them had a positive family history of breast and ovarian cancer." (PMID 30940100, 2019). "For example, a study enrolling patients with BRCA1/2-defective ovarian cancer demonstrated that patients with these mutations respond positively to platinum-based drug therapies." (PMID 31450627, 2019). "Here, we investigated the drug resistance‐associated regulation of BRCA1 in epithelial ovarian cancer stem cells (EOCSCs)." (PMID 30636383, 2019). "The value of cfDNA and serial samples has been investigated in five patients with ovarian cancer with intragenic mutations predicted to restore BRCA1/2 open reading frames, including two patients with multiple independent reversion alleles." (PMID 35582591, 2019). "GWA analyses identified several loci, which can modify the penetrance of BRCA1/2 pathogenic variants and the age at onset of hereditary breast and ovarian cancer to some extent." (PMID 31395037, 2019). "For example, the common polymorphism in OGG1 rs2304277 has been linked to BRCA1-deficiency in ovarian cancer." (PMID 31329989, 2019). "The PARP inhibitor olaparib, which was developed according to the principles of synthetic lethality, is the first drug for treating ovarian cancer carrying the BRCA1/2 mutation." (PMID 31590683, 2019). "In our study on BRCA1 methylation status and ovarian cancer risk, we performed extensive sensitivity analyses." (PMID 31225507, 2019). "Genetic testing for BRCA1/2 germline mutations in hereditary breast/ovarian cancer patients requires screening for single nucleotide variants, small insertions/deletions and large genomic rearrangements (LGRs)." (PMID 31741787, 2019).
ovarian carcinoma (continued). "Epidemiological studies have shown that the contraceptive drugs, BRCA1–2 mutations, and multiple ovulations can be associated with ovarian cancer." (PMID 31810474, 2019). "The most common clinical causes of HR deficiency are BRCA1/2 germline mutations, identified in 9% and 8% of the ovarian cancers, respectively." (PMID 31374917, 2019). "We then looked at the position of germline BRCA1 or 2 mutations in relation to their respective Ovarian Cancer Cluster Regions (OCCR)." (PMID 30821131, 2019). "This was based on the results of Study 42, evaluated olaparib in the dosage of 400 mg bid in heavily pretreated patients with recurrent, platinum resistant ovarian cancer, and a germline BRCA1/2 mutation, until disease progression or unacceptable toxicity." (PMID 31109041, 2019). "In this study, we comprehensively investigated multiple serum tumor markers and BRCA1/2 germline mutations in a Chinese cohort of ovarian cancer patients." (PMID 30972954, 2019). "The PARP inhibitor olaparib has been approved in the maintenance setting of platinum-sensitive epithelial ovarian cancer patients with germline or somatic BRCA1/2 mutation." (PMID 31653094, 2019). "The incidence of BRCA1/2 reversion mutations in women with platinum-resistant ovarian cancer has been reported as high as 46% (95% CI 29–65%)." (PMID 29464354, 2018). "In comparing ovarian cancer with benign ovarian disease in patients with BRCA1 mutation, ROMA had the best ROC-AUC, followed by CA125 and then by HE4." (PMID 29849823, 2018). "The FDA also approved olaparib as a single agent for the treatment of advanced ovarian cancer patients with germline BRCA1 or BRCA2 mutation who had received three or more prior lines of chemotherapy." (PMID 30050740, 2018). "This approach has so far demonstrated the most significant efficacy in breast and ovarian cancers with known BRCA1/2 mutations, with advanced FDA (Food and Drug Administration) approval granted for the treatment of BRCA-mutant ovarian and prostate cancers." (PMID 30120226, 2018). "Loss of BRCA1 is a common characteristic in breast and ovarian cancers and causes defects in DNA repair, especially double-strand breaks (DSBs) by homologous recombination (HR), resulting in genomic instability." (PMID 30176860, 2018). "Clinical data suggest the most impressive anti-tumour activity occurs in women with platinum-sensitive ovarian cancer and germline or somatic BRCA1/2 mutations (g/sBRCAmt)." (PMID 29464354, 2018). "And certain mutations of BRCA1/2 often lead to increasing the risk of breast and ovarian cancer in women." (PMID 30111351, 2018). "Breast cancer 1 (BRCA1) gene is a well-recognized tumor suppressor gene, and the loss of BRCA1 is closely associated with ovarian carcinoma." (PMID 30064416, 2018). "In general, mutations of BRCA1 are closely associated with induction of breast and ovarian cancers but are also known to contribute to the incidence of other cancers at a low frequency." (PMID 30652068, 2018). "The effectiveness of PARP inhibition in BRCA1/2-mutated breast and ovarian cancers are under extensive evaluation." (PMID 29784019, 2018). "For example, Fanconi anemia pathway is closed linked to breast and ovarian cancer susceptibility gene BRCA1." (PMID 30577793, 2018). "In summary, PARP inhibitors demonstrate a very promising safety profile and anti-tumor efficacy in patients with BRCA1 or BRCA2-mutated platinum-sensitive ovarian cancer patients in both treatment and maintenance settings." (PMID 30050740, 2018). "BRCA1 is a tumor suppressor whose mutation was correlated with the appearance of familial breast and/or ovarian cancer at young ages." (PMID 29922232, 2018). "Recent studies have implicated a plethora of factors involved in the ovarian cancer cisplatin resistance, including BRCA1 and BRCA2 mutations." (PMID 30061175, 2018).